ENSG00000238387
Synonyms: LOC124902827
Gene: Small nucleolar RNA gene on chromosome 11 (9,578,028 to 9,578,131, forward strand). Ensembl gene ENSG00000238387.
Gene Ontology:
Biological process: RNA processing
Cellular component: nucleolus
Homologues: Orthologues: rat LOC120094529 (62% identical). Paralogues in human: SNORD13P3 (83% identical), SNORD13 (82% identical), SNORD13E (81% identical), SNORD13P1 (79% identical), SNORD13D (78% identical).